Y_RNA (Y RNA )
Gene: Miscellaneous RNA gene on chromosome 1 (63,338,263 to 63,338,372, forward strand). Ensembl gene ENSG00000252784.
Homologues: Orthologues: chimpanzee Y_RNA (100% identical). Paralogues in human: Y_RNA (69% identical), Y_RNA (68% identical), RNY3 (67% identical), Y_RNA (67% identical), RNY3P2 (66% identical), Y_RNA (66% identical), RNY3P1 (65% identical), RNY3P9 (65% identical), Y_RNA (65% identical), RNY3P14 (65% identical), RNY3P4 (65% identical), RNY3P7 (65% identical), and 82 more.